TLR7 (toll like receptor 7)
Diseases named in the same sentence as TLR7 in open-access papers (continued):
Sharing a sentence is not in itself a finding about the gene and the disease.
lupus (continued). "TLR7 activation drives molecular, synaptic, cellular, and pain phenotype alterations in lupus mice." (PMID 41511304, 2025). "Furthermore, intrathecal administration of a TLR7 agonist enhanced hindlimb thermal sensitivity in control mice, while intrathecal administration of a TLR7 antagonist alleviated hindlimb thermal hypersensitivity in lupus mice." (PMID 41511304, 2025). "The hyperactivation of the TLR7 signaling pathway is a key factor in the pathogenesis of lupus." (PMID 40989817, 2025). "Further studies show that reduced XIST expression leads to female-specific lupus-like autoimmunity, while extracellular xist RNA itself may stimulate TLR-7 as an endogenous ligand." (PMID 41283475, 2025). "The molecular and genetic basis of enhanced TLR7 responses to SARS-CoV-2 in patients with chilblains has yet to be elucidated, although TLR7 hyperactivation is known to induce other autoimmune disorders including lupus, of which chilblains are a common cutaneous manifestation." (PMID 41347066, 2025). "The role of TLR7 in lupus is well recognized, but the role of TLR9 remains controversial." (PMID 40931063, 2025). "Comparison between vehicle-treated (n = 6) and ODN 2088-treated (n = 7) MRL/lpr mice confirmed that ODN 2088 significantly increased withdrawal latencies at 60 min and 90 min post-injection (p < 0.01), indicating that TLR7 blockade alleviates thermal hyperalgesia in lupus mice." (PMID 41511304, 2025). "These important studies provided evidence that enhanced TLR7 signaling could drive lupus, and mechanisms by which more TLR7 protein could be expressed." (PMID 40794441, 2025). "Regarding the mechanisms of B cell involvement in lupus lesions, studies have shown that autoreactive B cells can be recruited into the tissue in response to inflammatory signals such as interferon, IL-21, and TLR7/9." (PMID 39917309, 2025). "For instance, rare gain-of-function TLR7 mutations can cause monogenic pediatric SLE and mice with TLR7 over-expression due to a translocation between the X and Y chromosome develop a lupus-like illness." (PMID 40051623, 2025). "In imiquimod (IMQ)-induced lupus mice, Ly6Chi monocytes were increased in the lymph nodes and Ly6Clo monocytes expressing high levels of TLR7, adhesion molecules, and cytokines such as IL-6, were increased in the peripheral blood and infiltrated into the kidneys." (PMID 40746538, 2025). "Although new data highlight the role of the TLR7–MyD88 axis in lupus and its interaction with oxidative stress in the brain tissues of spontaneous lupus models, targeting this axis with antioxidants in induced neuropsychiatric lupus models has not been investigated." (PMID 39061948, 2024). "A potential role for TLR7 activation in promoting MetS is of particular interest due to evidence that increased TLR7 activation may contribute to the development of the autoimmune disease lupus, and that lupus is also associated with a high prevalence of MetS." (PMID 38346802, 2024). "In SLE (systemic lupus erythematosus), TLR7 and TLR9 have opposing effects on disease progression." (PMID 38892317, 2024). "The functional consequences of lowering the threshold of TLR7 activation were revealed when the Y264H variant was introduced into mice that otherwise were not prone to lupus." (PMID 38255243, 2024). "Defining the role of TLR7 in the induction of lupus in male SJL/J mice expressing transgenic XIST is therefore important for determining whether this mouse model is equivalent to the autoimmune model in humans." (PMID 38665922, 2024). "In mice, TLR7 overactivity appears to explain lupus disease in a large number of models." (PMID 38866437, 2024). "Bank1 deficiency decreases autoantibody production in TLR7.tg6 and IMQ-treated lupus-prone mice." (PMID 39163122, 2024).
lupus (continued). "Moreover, in vivo studies showed that treatment with PKM2 inhibitors significantly reduced the glomerular deposition of IgG and IgM in lupus mice induced by imiquimod (a TLR7 agonist) thus protecting the mice against lupus progression." (PMID 38914953, 2024). "TLR7-driven lupus is GC-independent and mostly ABC-dominant." (PMID 38271512, 2024). "Therefore, we studied the regulatory effect of lupus-derived MDSCs on the activation of TLR7 signaling." (PMID 38429401, 2024). "highlighted a potential protective role of GSDMD in imiquimod (a TLR7 agonist)‐induced lupus model." (PMID 38881675, 2024). "Recently, a role for IFN-λ in murine SLE was reported in a TLR7-induced lupus mouse model." (PMID 39737176, 2024). "Indeed, a recent preclinical study demonstrated that TLR7/8 inhibition increased the effect of glucocorticoids in lupus-prone mice and sensitized human PBMC against glucocorticoid treatment." (PMID 38791389, 2024). "Single knockout of Tlr7 in lupus-prone mice also ameliorated disease." (PMID 38791389, 2024). "In the present study, we investigated the role of MDSCs in TLR7-mediated lupus pathogenesis." (PMID 38429401, 2024). "In mice with TLR7-driven lupus, ZEB2 is essential for ABC formation and autoimmune pathology." (PMID 38271512, 2024). "Collectively, these data indicated that lupus MDSCs could promote the TLR7-mediated activation of macrophages and DCs in vitro." (PMID 38429401, 2024). "Furthermore, functional studies have demonstrated that a single genetic variation in TLR7 is sufficient to induce a lupus-like phenotype." (PMID 39427224, 2024). "Moreover, in the NZM/NZW lupus model, Ly6Clo monocytes, which spontaneously accumulate with age, express high levels of TLR7 protein, and administration of TLR7 agonist ligands accelerates Ly6Clo monocyte augmentation in the blood and promotes nephritis." (PMID 38701219, 2024). "Since we also know that TLR9’s negative regulation of lupus pathology requires its expression in B cells, this suggests that it may directly interact with TLR7 in some fashion, since TLR7’s role in driving disease is also B cell intrinsic." (PMID 37606042, 2023). "The role of TLR7 in lupus pathogenesis is enhanced when the regulatory role of TLR9 is absent." (PMID 37606042, 2023). "The results from this study do define a B cell–specific role for TLR7 in driving lupus pathology." (PMID 37606042, 2023). "According to additional research, focusing on the TLR7 pathway in lupus-prone models may provide insights for preventing the onset of serious disease." (PMID 36875095, 2023). "Mechanistically, the lupus genetic background could license the breach of gut barrier integrity in response to TLR7/8 activation through the gut dysbiosis that is present in TC mice, and that can transfer autoimmune activation in non-autoimmune mice." (PMID 37483626, 2023). "In summary, we showed that the activation of the TLR7/8 pathway, a common feature of lupus pathogenesis, may contribute to impaired gut barrier integrity but only in the presence of lupus genetic susceptibility." (PMID 37483626, 2023). "The lupus genetic background could also license the breach of gut barrier integrity in response to TLR7/8 activation through the immune system." (PMID 37483626, 2023). "Indeed, TLR7 activation by intestinal bacteria resulted in lupus-like disease, as Lactobacillus reuteri mediated TLR7-dependent lupus in both conventional and germ-free mice." (PMID 39916928, 2023). "Data from TLR7-induced lupus Ifnlr-/- mouse models support the mechanistic role of IFN-III in SLE." (PMID 37809098, 2023). "Specifically, the Tlr7-null lupus-prone mouse model lacks CD11c+T-Bet+CD21− B cells." (PMID 36875095, 2023). "TLR7-dependent translocation of Lactobacillus reuteri was confirmed to induce the increase in plasmacytoid dendritic cells (pDCs) and interferon signaling, which worsened autoimmune responses in systemic lupus erythematosus (SLE)." (PMID 35308555, 2022).
lupus (continued). "We hypothesize that the interstitial capillary injury is central to the cardiovascular response of lupus-prone mice to acute TLR7 activation as prolonged R848 treatments results in fatal hemorrhages in TC mice." (PMID 35860280, 2022). "TLR7 plays a critical role in the pathogenesis of lupus through the production of type I IFN." (PMID 35860280, 2022). "It has also been demonstrated that within exosomally delivered microRNAs in the plasma of patients with systemic lupus erythematosus (SLE) are potential novel TLR7 endogenous ligands that induce plasma cell-like DC (pDC) activation and the production of IFN-α and proinflammatory cytokines." (PMID 35242126, 2022). "Notably, pharmacological inhibition of the activity of ACK1 not only alleviated the conditions of TLR4-mediated endotoxic shock mice but also relieved the conditions of TLR7-mediated lupus model mice." (PMID 35669783, 2022). "Furthermore, TLR9-deficient mice, excluding the role of TLR9 in the inhibition of TLR7-mediated responses, show high lupus activity compared to WT mice." (PMID 36359746, 2022). "Additionally, gut leakage appears TLR7 dependent, since co-housing with lupus mice only resulted in leaky gut when the TLR7 gene was expressed." (PMID 35833129, 2022). "Interestingly, while this study concluded that Lactobacillus reuteri alone contributed to lupus development for TLR7-dependent mice, others have found removal of Lactobacillus spp." (PMID 35833129, 2022). "We tested the hypothesis that acute TLR7 activation by R848 may induce cardiovascular pathology in lupus-prone mice." (PMID 35860280, 2022). "In addition to the decrease in plasma NET levels in lupus mice treated with the TLR7 agonist, a significant decrease in anti-double-stranded DNA and anti-beta-2 glycoprotein autoantibodies was observed." (PMID 36133811, 2022). "Moreover, RS diet in TLR7.1Tg and tRA treatment in pristine-treated lupus mice also had a beneficial effect on Clostridiales." (PMID 36624775, 2022). "While these studies provide compelling evidence that TLR7 mediates SS, it is important to note that SS and lupus share overlapping disease features and so it is difficult to examine disease characteristics that result from SS specifically in the background of another autoimmune disease." (PMID 36591307, 2022). "However, the expansion of L. reuteri has been reported in spontaneous Tlr7 transgenic and inducible TLR7 lupus-prone mouse models." (PMID 35795671, 2022). "Conversely, TLR7 deletion completely suppressed lupus disease progression in TLR9−/− mice." (PMID 36555668, 2022). "Although TLR7 and TLR9 co-express on pDCs and B cells and share downstream signaling pathways, whether TLR7 and TLR9 signaling have different roles in immune regulation in lupus’ pathogenic mechanisms is still under investigation." (PMID 36555668, 2022). "Another recent study reported that supplementation with a high fibre-rich diet - providing the fuel for increased C3 levels by fermentation process of the gut microbiota - improved lupus-related disease manifestations in a Toll-like receptor 7-dependent lupus-like mouse model." (PMID 35880182, 2022). "In addition, syntenin-1 regulates the sorting of Toll-like receptor 7 (TLR7), which contributes to autoimmune diseases, such as systemic lupus erythematosus via recognition of self-RNA, into intralumenal vesicles of multivesicular bodies." (PMID 35628473, 2022). "Although lower levels of TLR7 responsiveness by male ABCs may protect DKO males from the development of lupus, the transcriptional profile of male ABCs showed enrichment for Rho GTPase signaling pathways." (PMID 34376664, 2021). "Notably, in this work, the authors highlight the TLR7 gene, located in the X chromosome and is involved in lupus pathogenesis, such as observed in the lupus-mice Yaa." (PMID 34769338, 2021).
lupus (continued). "Furthermore, 6-gingerol suppressed the production of proinflammatory cytokines, such as TNF-α and IFN-γ, similar to PDE4 inhibitors, therefore exerting an overall antiinflammatory effect in TLR7 agonist–induced lupus." (PMID 33373329, 2021). "The recognition of self–nucleic acids may directly activate B cells or sensitise them to BCR–mediated activation: the transgenic overexpression of Tlr7 or Tlr9 generates autoreactive PCs and triggers lupus–like disease in mice." (PMID 34163480, 2021). "In this study, we tested if TMAO can boost the tendency to SLE development and T cell activation and proliferation in secondary lymph organs, causing endothelial dysfunction and hypertension in a lupus model induced by epicutaneous application of the TLR7 agonist imiquimod (IMQ)." (PMID 35052589, 2021). "It has been shown that knockout of Atg5 in B cells attenuates the development of autoantibody production, lymphocyte infiltration and mortality in toll-like receptor 7-transgenic mice, supporting an important role for B cell autophagy in the development of lupus-like autoimmunity." (PMID 34335611, 2021). "Here, using a lupus-like mouse model that affects females more severely, the authors observe an ABC mediated and guanine nucleotide exchange factor (GEF) restrained pathogenic process involving TLR7." (PMID 34376664, 2021). "Studies in the context of systemic lupus erythematosus show that substantial fractions of immune cells, including primary B lymphocytes, monocytes, and DCs express TLR7 from both X-chromosomes, resulting in higher TLR7-driven functional responses in these cells." (PMID 34531867, 2021). "Next, the study showed that the AMPK agonist metformin and the mTOR inhibitors INK128 and rapamycin could reduce the percentage of M-MDSCs in mice with pristane-induced lupus and TLR7- and IFN-α-induced BM differentiation into MDSCs in vitro." (PMID 34282122, 2021). "Additionally, it alleviated the progression in the TLR7-agonist imiquimod-mediated lupus mice and spontaneous lupus MRL/lpr mice." (PMID 34025679, 2021). "The present study found that the percentage of M-MDSCs increased in mice with pristane-induced lupus, and the TLR7 signal activation and the high IFN-α level could promote the differentiation of M-MDSCs in vitro." (PMID 34282122, 2021). "Moreover, it alleviated the progression in the TLR7-agonist imiquimod-mediated lupus mice and spontaneous lupus MRL/lpr mice." (PMID 34025679, 2021). "Interestingly, the inhibition of TLR-7 in experimental lupus attenuated glomerulonephritis and lung injury." (PMID 34367133, 2021). "Currently, the specific contributions of TLR7/9 signaling to lupus pathogenesis are unclear." (PMID 32251357, 2020). "A recent study by Morawski and Bolland detailed the TCR repertoire of non-pathogenic CD8+ T cells in the brains of TLR7-transgenic (TLR7-tg) mice, another model for murine lupus." (PMID 32765512, 2020). "Although a variety of probiotics have demonstrated abundance of Lactobacillus (i.e. Lactobacillus GG), a recent study showed that Lactobacillus reuteri, a commensal Lactobacillus strain, drove autoimmunity in a Toll-like receptor 7-dependent mouse model of lupus." (PMID 32452830, 2020). "In mammals, Galectin-9 could inhibit TLR7-mediated autoimmunity in murine lupus models and suppress the apoptosis in human rheumatoid arthritis synovial fibroblasts." (PMID 32362893, 2020). "Understanding TLR7 as a mediator of lupus disease expression is also important for those studying sex bias in autoimmunity, since females are pre-disposed to TLR7-driven autoimmunity, and aberrant X chromosome inactivation was implicated in increased X-linked TLR7 gene dosage." (PMID 31998321, 2019). "In summary, we utilized the Yokogawa protocol for epicutaneous TLR7 stimulation to induce a lupus-like phenotype and observed mild autoimmunity in B6 mice and accelerated autoimmunity in NZM2410 mice, but did not observe significant nephritis or proteinuria in either strain." (PMID 31998321, 2019).
lupus (continued). "The pristane-inducible murine model of lupus, for example, is dependent on TLR7 signaling." (PMID 31998321, 2019). "Next, we utilized a well-established model of lupus of TLR7 overexpression (TLR 7.1)." (PMID 29786074, 2019). "Moreover, CD11c+CD11b+ B cells from aged mice and lupus-prone NZB/W mice both produced large amounts of anti-chromatin antibodies upon TLR7 ligation." (PMID 31795353, 2019). "TLR8ko mice on the C57BL/6 background develop lupus due to increased TLR7 expression by DCs." (PMID 31552019, 2019). "Importantly, treatment with both pCAGGS-Tgfb3 and pCAGGS-Il10 suppressed autoantibody productions in a murine lupus model induced with TLR7 agonist, imiquimod." (PMID 29963056, 2018). "DNA and RNA are major autoAgs in lupus that can stimulate immune cells through TLR7 and TLR9." (PMID 29850618, 2018). "Numerous mouse studies also demonstrated the dichotomy of TLR9 and TLR7 in lupus pathogenesis." (PMID 30286201, 2018). "Its expression increases by Toll-like receptor 7 (TLR7) stimuli in plasmacytoid DCs from New Zealand Black/White F1 hybrid (NZB/W F1) mice with symptomatic lupus, leading to the expression of the CD40 co-stimulatory molecule required to facilitate the T cell activation." (PMID 30322050, 2018). "The dichotomy of TLR9 and TLR7 pathways in lupus suggests anti-dsDNA B cells and anti-ssRNA B cells may respond differently to their respective autoantigens." (PMID 30286201, 2018). "However, the IFN-α-producing capacity of lupus pDCs was enhanced following stimulation with a TLR7 agonist and correlated with disease activity and serum IFN-α." (PMID 29052537, 2017). "The myeloid expansion observed here is consistent with reports of enhanced myelopoiesis in mice engineered to transgenically overexpress Tlr7 and of monocytosis in aged male BXSB mice, a lupus model in which disease is driven by the yaa translocation that increases gene dosage of Tlr7 among others." (PMID 28278279, 2017). "Importantly, enhanced cytokine production by pDCs was elicited not only by synthetic ligands of TLR7 or TLR9 but also by natural ligands such as self nucleic acid-containing immune complexes present in the sera of systemic lupus erythematosus (SLE) patients." (PMID 28239379, 2017). "Inhibitory oligonucleotides whose guanine moiety has been modified have been found to inhibit production of Type I IFNs by human pDCs as well as pDCs from MRL/lpr mice model of lupus which were stimulated via TLR7 and TLR9 agonists, identifying another potential therapeutic route in lupus." (PMID 32185249, 2017). "Indeed, deletion of the TLR7 gene in lupus mice suppresses the production of autoantibodies to RNA-associated proteins and ameliorate systemic autoimmunity." (PMID 28456914, 2017). "We next found that the changes in expression of nine of these twelve adhesion molecules were significantly upregulated on brain-infiltrating CD8+ T cells in TLR7[Tg] lupus-prone mice; namely CD49d, CD11a, CD31, CD54, CD49f, CD29, CD48, and CD43aag, as well as CD44 and CD103." (PMID 28098193, 2017). "However, the TLR7 agonist-induced IFN-α producing capacity of lupus pDCs was enhanced and correlated with disease activity and serum IFN-α." (PMID 29052537, 2017). "Data from murine lupus models further support a role for TLR7 in SLE pathogenesis." (PMID 28506291, 2017). "We identified a novel regulation of CD40 expression by miR-155, by which may contribute to the hyperactivated TLR7 response in lupus pDCs." (PMID 27509492, 2016). "In addition, nucleic acid self-antigens and/or nucleic acid-containing ICs are another potential inducer of TLR7/9-dependent IFNα production by pDC in lupus." (PMID 27034965, 2016). "yaa mouse, a lupus model that develops disease through exacerbated TLR7 expression." (PMID 27228057, 2016). "Overall, our findings suggest that the elevated miR-155 induction may contribute to the enhanced TLR7-induced CD40 expression in pDCs derived from BM of lupus mice." (PMID 27509492, 2016).